MMP17 (matrix metallopeptidase 17)
Diseases named in the same sentence as MMP17 in open-access papers (continued):
Sharing a sentence is not in itself a finding about the gene and the disease.
tumor (23 papers, 2011 to 2025). "Since the depth of tumor invasion, lymph node metastasis and serous membrane involvement were closely associated with tumor progression, MMP17 and MMP25 were associated with tumor progression." (PMID 25621036, 2015). "Our findings revealed a mechanistic link between CCZ1 and MMPs, particularly MMP2 and MMP17, which are known regulators of tumor invasion and metastasis." (PMID 39062041, 2024). "Mounting evidence suggests that dysregulation of MMPs, particularly MMP2 and MMP17, plays a pivotal role in tumor invasion, metastasis, and the microenvironment in various cancer types." (PMID 39062041, 2024). "MMP2 and MMP17 have been implicated in extracellular matrix (ECM) degradation, angiogenesis, and the facilitation of tumor cell migration and invasion, which contribute to disease progression and poor patient outcomes." (PMID 39062041, 2024). "The expression levels of TLL1, HMCN2, FREM2 and MMP17 were significantly higher in normal ovarian tissues than in tumour tissues." (PMID 37388244, 2023). "In the clinicopathological analyses, upregulated MMP11, MMP14, MMP16, MMP17, MMP19, and MMP23B were significantly associated with a higher tumor stage." (PMID 34804973, 2021). "While the vast majority (86–97%) of microglia showed expression of individual MT-MMPs, we observed significant differences in the proportions of MMP expression in tumor cells: MMP14 was produced by 54%, MMP16 by 80%, and MMP17 by 90% of tumor cells." (PMID 32872536, 2020). "Proteolytic enzymes such as ADAM28, MMP12 and MMP17, which can enhance extracellular invasion and expansion of tumor volume, were also upregulated in the irradiated SJGBM2-10gy cells." (PMID 30344926, 2018). "The expression of MMP17 and MMP25 was significantly associated with the depth of tumor invasion, lymph node metastasis and serous membrane involvement (P<0.05), but not with patient age and gender, or lesion length, site and histological grade (P>0.05)." (PMID 25621036, 2015). "On the other hand, we retrieved the metalloproteinase 17 (MMP17) to be up-regulated in the tumours with high expression of miR-34a." (PMID 22102859, 2011). "The expression of PER1, AKAP12 and MMP17 was located in the cytoplasm of tumor cells." (PMID 37434173, 2023). "In addition, their analysis showed that the upregulation of MMP11, MMP14, MMP17, and MMP19 is significantly associated with a more advanced tumor stage and a worse long-term prognosis." (PMID 37511338, 2023). "Also, in the clinicopathological and prognosis analyses, upregulated MMP11, MMP14, MMP17, and MMP19 were significantly associated with a higher tumor stage and a worse prognosis." (PMID 34804973, 2021). "Of note, Mmp17 expression was restricted to muscle cells also in tumor areas." (PMID 34795242, 2021). "Furthermore, the expression levels of tumor invasion-associated genes (MMP17 and ITGA3) were enriched in organoids (and tumor)." (PMID 30353124, 2018). "Patient D3 carries a private mutation in MMP17 in the primary tumour (c.G371A, p.R124K), which is absent from the synchronous metastasis." (PMID 28120820, 2017). "In addition to the cancer cells, MMP17-positive staining was also observed in nearby cancer stromal cells, which suggested that stromal cells have an important role in the process of tumor invasion and metastasis." (PMID 25621036, 2015). "MMP-17 promotes primary tumor growth and lung metastasis in preclinical models." (PMID 21152183, 2011). "A total of 22 MMPs were found to be abnormally expressed in UCEC tumor tissues, with MMP11 and MMP17 significantly enriched in the tumor’s ECM." (PMID 41228294, 2025). "Analysis of the DEGs in TCGA tumours revealed that the miR-18a/low tumours expressed high levels of EMT master regulators-ZEB1 and ZEB2 and Matrix metalloproteinases, MMP2, MMP3, MMP10, MMP11, MMP13 and MMP17 (p < 0.05)." (PMID 38786043, 2024).
tumor (continued). "We also evaluated the protein level of MMPs in our patients and measured the expression level of MMP1–MMP3, MMP7–MMP9, MMP11, MMP12, MMP14, MMP17, MMP19, and MMP28 in their tumor tissue and adjacent normal tissue by Western blot." (PMID 34804973, 2021). "MMP11, MMP14, MMP16, MMP17, MMP19, and MMP23b were positively correlated with the tumor stage, that is, the mRNA levels of MMPs in patients with higher tumor stage were always high." (PMID 34804973, 2021). "Moreover, infiltration of natural killer (NK), mast, and NK CD56 bright cells was enhanced in tumor tissues with high MMP11 and MMP17 expression." (PMID 41228294, 2025). "We did not observe differences in tumor diameter suggesting that MMP17 mediates tumor initiation but not tumor progression." (PMID 34795242, 2021). "The fraction of cells that produced MT-MMPs showed differences with regard to the particular MMPs and the location (infiltration zone vs. solid part of the tumor): 51% vs. 54% were positive for MMP14, 65% vs. 74% produced MMP16, and 62% vs. 86% expressed MMP17." (PMID 32872536, 2020).
cancer (12 papers, 2013 to 2025). A tumor composed of atypical neoplastic, often pleomorphic cells that invade other tissues. "MMP-17 (MT4-MMP) is associated with inflammation and angiogenesis and is related to the progression of various cancers." (PMID 39796177, 2025). "On comparison of the expression of PER1, AKAP12, and MMP17 in TCGA with that in the GTEx dataset, the levels of the three genes were higher in normal ovarian tissues than in cancer tissues." (PMID 37434173, 2023). "Similar to many other MMPs, clear roles for MMP-17 (also called MT4-MMP) have been described within the context of cancer." (PMID 34255809, 2021). "MMP17, PI3, TLL1, ANGPTL4, and TGFBI have all been previously associated with cancer." (PMID 37388244, 2023). "HCC patients with increased numbers of cancer stem cells also displayed an accumulation of a HIF-1α-driven SPP1+ macrophage subset characterized by the expression of MMPs (MMP9, MMP12, and MMP17), which may enhance cancer epithelial‒mesenchymal transition." (PMID 40721870, 2025). "Activation of Slug by HIF-1α increased the expression of membrane-type 4 matrix metalloproteinase (MT4-MMP, also known as MMP-17) in human cancer cells, which promotes in vitro invasiveness of the cells and in vivo colonization and growth of the cells in the lungs, via an EMT-independent mechanism." (PMID 25937967, 2014). "MMP17 is a protease anchored to the membrane and involved in ECM remodeling in physiologic processes such as tissue regeneration/repair and inflammation, but also involved in pathologic processes of cancer where it may play a role in cancer progression." (PMID 37686244, 2023).
infection (2 papers, 2021 to 2023). The state of being infected such as from the introduction of a foreign agent such as serum, vaccine, antigenic substance or organism. "This study explores the role of MMP17, which is preferentially expressed by smooth muscle cells in the intestine, in intestinal homeostasis and during immunity to infection." (PMID 37869014, 2023). "Mmp17 KO mice, infected with a low dose of T. muris eggs, were able to clear the infection, while WT mice developed a chronic infection." (PMID 37869014, 2023). "In our previous in vitro study of E. tenella infected chicken macrophages, MMP9 expression was transiently up-regulated at 12 hpi while MMP10 and MMP17 expression was up-regulated later in the infection at 48–72 hpi (unpublished observation)." (PMID 34521339, 2021). "Mice lacking MMP17 expressed high levels of goblet-cell associated genes and proteins, such as CLCA1 and RELM-β, which are normally associated with immune responses to infection." (PMID 37869014, 2023). "However, when challenged with a low dose of the helminth Trichuris muris, Mmp17 KO mice had increased resistance, without a clear role for an altered immune response during infection." (PMID 37869014, 2023).
psychiatric diseases (1 paper, 2022). "Our results showed that MMP genes such as MMP-15, MMP-16, MMP-17, MMP-24 and MMP-28 were expressed highly or moderately in brain, implying the values in investigation of more genes in association with psychiatric diseases." (PMID 35444067, 2022).
MMP17 also shares sentences with these, for which no sentence is quoted: adenomyosis (1 paper); asthma (1); astrocytomas (1); bacterial infections (1); brain tumors (1); breast adenocarcinoma (1); cervical squamous cell carcinoma (1); ependymoma (1); glioblastoma (1); head and neck cancer (1); melanoma (1); oligodendroglioma (1); ovarian carcinoma (1); pancreatic cancer (1); serous ovarian carcinoma (1); squamous carcinomas (1).